HIF1A (hypoxia inducible factor 1 subunit alpha)
Diseases named in the same sentence as HIF1A in open-access papers (continued):
Sharing a sentence is not in itself a finding about the gene and the disease.
cancer (continued). "HIF-1a is a key transcriptional factor for hypoxia-induced glycolysis in cancer, which is differentially regulated by diverse lncRNAs." (PMID 35978828, 2022). "High level of HIF-1α promotes cancer progression through multiple mechanisms, including angiogenesis, cell proliferation and survival, invasion and metastasis, and therapy resistance." (PMID 36071871, 2022). "We have previously shown that Ca2+ mobilization affects both the p-Akt and HIF-1α levels in cancer epithelial cells." (PMID 35163310, 2022). "HIF1α-dependent induction of PDK1 is associated with glycolytic reprogramming, enhanced cancer cell proliferation and stemness in several tumors." (PMID 36340043, 2022). "ECM is known to bind to the hypoxia response element and this is the primary mechanism by which it interacts with HIF-1α in cancer cell lines." (PMID 35928940, 2022). "HIF-1α is an oxygen-sensitive transcription factor that regulates LDHA transcription in human cancers." (PMID 35757505, 2022). "αKG is a co-substrate of PHD, the activity of which induces HIF-1α degradation and as a result, changes in the proliferation of cancer cells until cancer growth arrest occurs." (PMID 36551876, 2022). "M2 macrophages, which are associated with cancer progression and invasion secret increased IL-1β under conditions of FAO dependence and HIF-1α upregulation." (PMID 35902970, 2022). "Studies demonstrated that IDH2/HIF1α pathway was responsible for cancer proliferation, such as cervical cancer and lung cancer." (PMID 36304962, 2022). "In fact, it has been reported that miRNAs regulate the expression of STAT3 through transcription factors such as NF-κB or HIF-1α, with the latter closely related to hypoxia in cancers such as leukemia or colon cancer." (PMID 35565420, 2022). "The expression level of the hypoxia-inducible factor (HIF)-1α subunit is low in cancer cells under normal oxygen saturation, because HIF-1α subunits are degraded by ubiquitin-protease hydrolysis complexes, immediately after translation." (PMID 36274852, 2022). "Wondonin (SL.18) as a HIF-1α degrader, has significant potential in clinical applications against cancer." (PMID 36014432, 2022). "HIF-1α is a critical transcription factor in mediating cancer metabolic reprogramming in response to hypoxia, including glycolysis and oxidative phosphorylation." (PMID 35906392, 2022). "Hypoxia promotes the expression of HIF-1α, a key transcription factor that regulates the expression of different genes related to various aspects of cancer biology, such as cell proliferation, angiogenesis, and glucose metabolism." (PMID 35845307, 2022). "In each section and subsection, we first summarized the role of hypoxia/HIF-1α on hallmarks of cancer as a background, then we reviewed the specific literature on GC." (PMID 35681691, 2022). "To explore the mRNA expression landscape of HIF1α in human pan-cancer, we comprehensively analyzed the mRNA expression levels of HIF1α in interactive body maps using the GEPIA dataset." (PMID 35860430, 2022). "As there are very few reports on efficient usage of some HIF-1α targeting drugs against certain type of cancers by clinicians, the pharmacological potential of common and newly proposed HIF-1α inhibitors should be properly documented." (PMID 36014432, 2022). "LSD1 can downregulate the Wnt pathway antagonists APC2 and DKK1 through demethylation in thyroid cancer, thus inhibiting APC2 transcription and activating the HIF-1α/DKK1 axis to regulate cancer progression." (PMID 36059955, 2022). "Not only does let-7C inhibit aerobic glycolysis by targeting HIF-1α, but it also found to modulate cancer progression and metabolism via inhibiting the lin28/PDK1 pathway." (PMID 36076967, 2022).
cancer (continued). "The expression of HIF-1α protein increased significantly in THP-1 macrophages co-cultured with cancer cells treated with lactate, and the HIF-1α pathway was involved in coordinating PD-L1-mediated immune escape." (PMID 36686771, 2022). "Digoxin (DIG) (PubChem CID: 2724385), a cardiac glycoside, has been demonstrated to have an anti-cancer effect in vitro and in vivo in various solid tumors by inhibiting HIF-1α production." (PMID 35432450, 2022). "It is well known that TLR4 and HIF-1α contribute to the progression of numerous inflammatory diseases, including cancer." (PMID 35464826, 2022). "HIF-1α knock-down resulted in the abrogation of the USP22-enhanced cancer stemness and glycolysis under hypoxic conditions." (PMID 36497394, 2022). "A hypoxic microenvironment with elevated HIF1A that promotes cancer growth and creates anticancer drug resistance has been reported in patients treated with TACE and TKI treatments." (PMID 36530994, 2022). "By using a well-characterized cancer cell line as a homogenous hepatocyte population, we also demonstrate that an approximate 10% reduction in oxygen triggers translocation of Hif1α to the nucleus and reduces albumin production." (PMID 36496994, 2022). "For better understanding role of HIF-1α in cancer cell metabolism, angiogenesis, metastasis, and survival of cancer stem cells are discussed here." (PMID 36014432, 2022). "Taken together, these results indicate that the HIF-1α/HSP90 pathway plays a critical role in inhibiting cancer cell progression." (PMID 35408505, 2022). "As a selective HIF-1α inhibitor, PX-478 interferes with HIF-1α and induces cell cycle arrest in cancer cells." (PMID 36439690, 2022). "HIF-1α and -2α overexpression promotes cancer cell invasion and drives EMT by a number of biochemical and genetic processes including Twist transcription, Snail nuclear localization and the consequent loss of E-cadherin and increase in mesenchymal markers." (PMID 36344992, 2022). "On the other hand, SRC, CASP3, EGFR, ERBB2, mTOR, MMP9, and HIF1A followed the proteoglycans in cancer." (PMID 35959427, 2022). "For instance, fumarate inhibits prolyl-hydroxylases, which leads to an increase in HIF-1α levels and allows, among other things, the survival of cancer cells exposed to hypoxia." (PMID 35273500, 2022). "Collectively, our analyses indicate that HIF1A promotes cell survival in early prostatic lesions and progression to malignant tumors." (PMID 35867798, 2022). "It is known that induction of HIF-1α upon hypoxia exposure drives EMT that is closely linked to chemoresistance and VM formation in cancer." (PMID 34969360, 2022). "Mechanically, SNHG11 can bind to pVHL and protect HIF1A from the degradation, accumulating HIF1A in the cancer cells." (PMID 35846431, 2022). "We found that KDM6B occupies the promoter HIF1α and regulates its expression in matrix-detached cancer cells Hypoxia regulates global transcription in multiple ways, and regulation of the expression and activity of histone demethylases is one of them." (PMID 35186918, 2022). "Subgroup analysis with regard to cancer type showed a positive correlation between HIF-1α expression and poor OS in EsoC, GC, and CRC." (PMID 35845307, 2022). "With the increasing level of HIF-1α and progressive hypoxia in the cancer cells, signals for new blood vessel formation is initiated through the process of neoangiogenesis." (PMID 36276103, 2022). "Further validation of the cross-talk between GSK3α expression and regulation of the HIF1/VEGFA signaling pathway, both in vivo and in vitro, revealed that GSK3α-mediated cancer tumor angiogenesis was dependent on HIF1α expression in vitro." (PMID 35292059, 2022). "Considering that targeting the upstream signaling of HIF-1α is also a potential strategy in cancer therapy, we aimed to investigate the effect of co-targeting of STAT3 and AKT, which are upstream of HIF-1α function." (PMID 35236823, 2022).
cancer (continued). "While elevated expression of CD73 in cancer cells is directly associated with HIF1α and lactate dehydrogenase 5 (LDH5) expressed by cancer cells, the expression of CD39 by cancer-associated fibroblasts is directly linked with PD-L1 expression by cancer cells." (PMID 36233088, 2022). "The expression of CD47 is upregulated by HIF-1α in triple-negative breast cancer cells resulting in a stem cell phenotypic switch through which cancer cells escape from phagocytosis." (PMID 35795658, 2022). "Several cancer medicines can target HIF-1-α (hypoxia-inducible factor-1-α) because they are essential in cancer cell growth." (PMID 36015667, 2022). "Several studies have demonstrated that hypoxia-inducible factor-1 alpha (HIF-1α) expression increases in various cancers and plays an important role in cancer cell progression." (PMID 35885540, 2022). "In hypoxic conditions, HIF-1α promotes enrichment of cancer stem cells (CSCs) to adopt a different way to survive." (PMID 36014432, 2022). "It is known that miR-138 can target HIF-1α, which can transcriptionally activate more than 100 downstream genes in response to changes in oxygen, thereby promoting cancer progression." (PMID 35703312, 2022). "We performed a pan-cancer search for HIF1A and HIF2A through TCGA databases, and HIF1A and HIF2A were found to be differentially expressed in many same or different cancers." (PMID 35774500, 2022). "PX-478 acting as a HIF1α inhibitor has antitumor activity against a variety of cancer cell lines under constant hypoxia in vitro and in vivo." (PMID 35874739, 2022). "For example, NT5E is associated with HIF-1-α transcription factor network, and many genes induced by HIF-1-α are highly expressed in cancer, including angiogenic growth factors (VEGF for example) and glucose metabolism enzymes." (PMID 36070312, 2022). "A careful examination of more cell functions influenced by HIF1A-targeting MEG3 on cancer cells is warranted." (PMID 36230902, 2022). "2ME2, a natural metabolite of estradiol inhibiting transcriptional activities of HIF-1α, showed strong antiangiogenic and antiapoptotic effects on cancer cells." (PMID 36551540, 2022). "Hif1α activates transcription of Pfkfb4, which leads to enhanced glycolysis and increased ATP production in cancer cells." (PMID 35917405, 2022). "A recent study showed that downregulating the HIF-1α/NOTCH-1 pathway was able to eliminate CD44+ cancer stem-like cell phenotypes to enhance the malignancy and chemo-resistance in neck squamous cell carcinomas." (PMID 36358852, 2022). "Hypoxia is often an environmental feature of EMT, and activated HIF-1α induces cancer EMT through multiple molecules and pathways, including inflammatory cytokines, epigenetic regulators, and transcription factors." (PMID 36532768, 2022). "Results showed that cancer cells treated with TIGIT and HIF-1α siRNA-loaded SPIONs-CL-FA NPs strongly suppressed the TIGIT and HIF-1α expression and cancer angiogenesis." (PMID 36532768, 2022). "The level of the HIF-1α negatively correlates with the degree of cell differentiation, proving that more undifferentiated and less mature and specialized cells, like cancer cells, tend to contain more HIF-1α." (PMID 36139678, 2022). "Early studies have reported that HIF1α is overexpressed in various cancer types and regulates the expression of most genes involved in many essential biological and pathological processes." (PMID 35508480, 2022). "Inhibition of proliferation and apoptosis induction of cancer cells by apigenin were associated with the downregulation of GLUT1 expression, which was partly dependent on the inhibition of HIF-1α." (PMID 36230492, 2022).
cancer (continued). "Since there is a certain relationship between HIF1α and immune response, we performed a pan-cancer analysis of the relationship between HIF1α expression and immune infiltration levels based on the TIMER database." (PMID 35860430, 2022). "Further research on the effect of hypoxia-induced HIF-1α stabilization on BAP1 would shed light on new molecular mechanisms of various events including cell death in cancer." (PMID 35205167, 2022). "MUC1 can not only mediate hypoxia-driven angiogenesis by regulating a variety of angiogenic factors; it can also stabilize and activate hypoxia inducible factor-1α (HIF-1α) to promote the metabolic reprogramming of cancer cells." (PMID 35879749, 2022). "Dysregulations of the TCA cycle impair prolyl hydroxylases’ (PHD) activity, the enzymes responsible of destabilization of HIF-1α, a master regulator of functional adaption to hypoxia in cancer cells." (PMID 36551876, 2022). "Hypoxia-inducible factor-1α (HIF-1α) enhanced aerobic glycolysis by binding to hypoxia-responsive elements of glycolytic gene promoters in cancer cells." (PMID 35869499, 2022). "Herein, we use bioinformatics to comprehensively and systematically study the role of HIF1α in human pan-cancer." (PMID 35860430, 2022). "Once stabilized under hypoxic conditions, HIF-1α upregulates many genes essential for cancer development." (PMID 35740392, 2022). "HIF-1α is an essential modulator of cancer cell metabolism, as it orchestrates the dysfunctional adaptations of mitochondria to the hypoxic conditions of cancer." (PMID 36506071, 2022). "The role of HIF1α in cancer development extends a broad spectrum of biological functions, such as promoting metastasis, reprograming metabolism, regulating cell proliferation and survival, and increasing therapeutic resistance." (PMID 35355718, 2022). "In contrast, many cancer cells, even in the presence of elevated HIF-1α levels, have been shown to maintain proliferation." (PMID 35932303, 2022). "HIF-1α activation leads to the upregulation of a number of genes involved in cancer cell survival and growth, including vascular endothelial growth factor (VEGF)." (PMID 36233505, 2022). "In some types of cancer, HIF-1α triggers apoptosis, whereas in some cases it induces cell proliferation." (PMID 36014432, 2022). "Hypoxia plays an important role in the maintenance of MDSCs through the HIF-1α-mediated expression of ectonucleoside triphosphate diphosphohydrolase 2 in cancer cells." (PMID 36551635, 2022). "HIF-1α expression was significantly high in cancer tissues in comparison to normal tissues (P < 0.0001)." (PMID 35496046, 2022). "Under normoxia, INF-γ was able to stabilize HIF-1α in various cancer cell lines and in human aortic valve interstitial cells." (PMID 36497143, 2022). "Tumors release succinate into the TME and activate the succinate receptor, which triggers the PI3K/HIF-1α signaling axis to polarize macrophages to TAMs and promote cancer cell migration and invasion." (PMID 35794625, 2022). "HIF-1α plays an important role in several diseases, such as cancer, cardiovascular disease, nephropathy, mood disorder, and musculoskeletal disorders." (PMID 35865944, 2022). "In summary, these findings provide insights into the growing interest in HIF1α between the diagnosis and treatment of cancer." (PMID 35860430, 2022). "In several cancer types, the stabilization of HIF1α leads to the upregulation of glycolytic metabolic pathways to produce ATP, strengthening the typical cancer Warburg effect." (PMID 36340043, 2022). "From the lncRNA-mRNA pathway network, PYCARD, RIPK2, and CASP1 were found to be significantly enriched in the NOD-like receptor signaling pathway, whereas MAP2K2, LUM, RPS6, PDCD4, TWIST1, and HIF1A were significantly enriched in proteoglycans in cancers." (PMID 36619896, 2022).
cancer (continued). "In conclusion, the present paper discovered that CNN1 functions as a cancer repressor gene that inhibits BC cell proliferation and migration and represses glycolysis by regulating HIF-1α pathway." (PMID 35903683, 2022). "Benoit Vlaminck’s team noted that echinomycin increased HIF-1α activity under normoxia and that it had a dual effect on HIF-1α activity, thus suggesting that the specificity of echinomycin as a cancer therapeutic agent is limited." (PMID 36139386, 2022). "HIF1A rewires cancer cell metabolism in hypoxic PDAC, not only to sustain ATP levels but also, predominantly, to limit reactive oxygen species (ROS) production, since mitochondria under hypoxia were shown to produce excessive amounts of ROS." (PMID 36612058, 2022). "HIF-1α is well known for its ability to modify cancer cell metabolism by inducing the overexpression of different glycolytic enzymes." (PMID 35202089, 2022). "This approach triggers the activation of an epithelial-mesenchymal transition in cancer cells while stimulating the expression of HIF-1α." (PMID 35628446, 2022). "The observations showed that silencing HIF-1α gene expression eventually inhibits P-gp expression, enhancing the sensitivity of cisplatin in multidrug-resistant cancer cells." (PMID 36153528, 2022). "To assess the clinical relevance of our findings, we showed the physical interaction of HIF1α and PRMT2 in cancer-associated adipocytes of human luminal-type BC specimens obtained commercially." (PMID 35593921, 2022). "When the HIF-1α is blocked, it also negatively regulates lactate uptake into carcinoma cells by inhibiting both MCT1 and MCT4 expression, as a result, retaining the carcinoma cell growth." (PMID 36612084, 2022). "The positive staining of Hsp70, MMP14, MMP2, and cortactin was mostly observed in the cytoplasmic of the carcinoma cells, whereas the nucleic positive signals were detected much more in the Hif1α immunohistochemical staining." (PMID 35957827, 2022). "As the phenomenon of lactate promoting the intracellular ROS levels has been observed in other cell lines, reduced lactate production is likely to negatively influence the stabilization of HIF-1α in carcinoma cells via decreased ROS." (PMID 36612084, 2022). "In prostate cancer, inhibiting lactate import into the carcinoma cells cripples the stabilization and activation of HIF-1α and subsequently impaired cell invasive skills." (PMID 36612084, 2022). "It is reported that HIF-1α has the function of regulating glucose metabolites by switching mitochondrial respiration to cytosolic glycolysis in cancer cells." (PMID 34368116, 2021). "Previous studies report that HIF-1α is involved in regulating the malignant biological behaviors of cancer cells, such as cell proliferation, migration and angiogenesis, in several types of cancer." (PMID 34036383, 2021). "The HIF-1α together with the AMP-activated protein kinase (AMPK) plays an important role in the reprogramming of cancer cells." (PMID 34681703, 2021). "This in vitro study with neuroglioma cells demonstrated that inhalational anesthetics exerted the anti-cancer effects via the miR-138/HIF-1α, miR-210/HIF-1α and miR-335/MMP9 pathways in this specific cancer cell line." (PMID 33919449, 2021). "The present study confirms that HIF-1α plays an essential role in the functional transformation of TGF-β in cancer cells." (PMID 34930376, 2021). "Downregulation of UBE2O promoted AMPKα2-mediated suppression of the (mTORC1)-HIF-1α pathway, which is essential for metabolic “reprogramming” of cancer cells." (PMID 33810518, 2021). "As an essential enzyme in the glycolytic pathway, it is proved that PGK1 is directly regulated by HIF-1α in many cancer types." (PMID 34291087, 2021). "HIF1α is also stabilized in cancers under normoxia, presumably due to dysregulation of its degradation pathway." (PMID 33572152, 2021).